IRAK4 (interleukin 1 receptor associated kinase 4)
Diseases named in the same sentence as IRAK4 in open-access papers (continued):
Sharing a sentence is not in itself a finding about the gene and the disease.
osteoarthritis (3 papers, 2021 to 2023). A noninflammatory degenerative joint disease occurring chiefly in older persons, characterized by degeneration of the articular cartilage, hypertrophy of bone at the margins and changes in the synovial membrane. "IRAK4 is significantly up-regulated in the synovium of osteoarthritis, and Ad-shIRAK4 decreased its expression via inhibiting the TLR/IL-1R signaling pathway and alleviated synovitis and cartilage degeneration." (PMID 37158847, 2023). "Using IHC analysis, we also found that IRAK4 is upregulated in synovium from the osteoarthritis rabbit model." (PMID 34863246, 2021). "IRAK4 is significantly upregulated in the synovium from the osteoarthritis rabbit model." (PMID 34863246, 2021). "Furthermore, by western blot, we found that, compared with the control group, IRAK4 protein expression significantly increased in synovium from the osteoarthritis rabbit model." (PMID 34863246, 2021). "This experiment explored the key role of IRAK4 in the osteoarthritis rabbit model." (PMID 34863246, 2021). "The results of this study show that Ad-shIRAK4 reduced the expression of IRAK4 and suppressed TLR/IL-1R signaling in the synovium from the osteoarthritis rabbit model." (PMID 34863246, 2021). "Ad-shIRAK4 reduced the expression of IRAK4 and suppressed TLR/IL-1R signaling in the synovium from the osteoarthritis rabbit model." (PMID 34863246, 2021). "In addition, Ad-shIRAK4 reduced the expression of IRAK4 and suppressed TLR/IL-1R signaling in the synovium from the osteoarthritis rabbit model." (PMID 34863246, 2021). "Furthermore, we investigated if adenovirus-encoded short hairpin (sh) RNA (Ad-shIRAK4) reduced the expression of IRAK4 and suppressed TLR/IL-1R signaling in synovium from the osteoarthritis rabbit model." (PMID 34863246, 2021).
psoriasis (3 papers, 2017 to 2025). An autoimmune condition characterized by red, well-delineated plaques with silvery scales that are usually on the extensor surfaces and scalp. "The scaffold function of IRAK4 plays a pivotal role not only in TLR4-mediated ALI, but also in TLR7/8-mediated psoriasis and TLR7/9-mediated SARS-CoV-2 infection." (PMID 40771916, 2025).
acute lymphoblastic leukemia (2 papers, 2014 to 2016). Leukemia with an acute onset, characterized by the presence of lymphoblasts in the bone marrow and the peripheral blood. "Elevated levels of IRAK1 and IRAK4 mRNA have been found in T acute lymphoblastic leukemia (T-ALL) cells." (PMID 27845762, 2016). "We recently found that IRAK-4 signaling in T cell acute lymphoblastic leukemia (T-ALL) is critical for their ability to proliferate but did not induce cell death (Li, unpublished data)." (PMID 25452754, 2014).
allergic disease (2 papers, 2011 to 2023). An immune response that occurs following re-exposure to an innocuous antigen, and that requires the presence of existing antibodies against that antigen. "Further studies including gene-gene and gene-environment interactions in AR cohorts are needed to clarify the impact of IRAK-4 on allergic disease." (PMID 21738793, 2011). "However there is no GWAS particularly for AR and moreover, no study reports a genetic association between IRAK-4 and allergy/atopy from GWAS approach." (PMID 21738793, 2011).
atherosclerosis (2 papers, 2017 to 2025). A disease characterized by the build-up of fatty material and calcium deposition in the arterial wall resulting in partial or complete occlusion of the arterial lumen. "The “Lipid and Atherosclerosis” pathway highlights HSP90AB1, IRAK4, and JAK2, which are associated with lipid metabolism and immune responses." (PMID 40621499, 2025). "Genes IRAK4, HDAC9, ACSL1 and APPL159 are recently reported as atherosclerosis causing genes in T2DM patients." (PMID 28761062, 2017).
Cyclic neutropenia (2 papers, 2016 to 2020). "Previous case reports describing P. aeruginosa sepsis in children with known PIDs, such as Wiskott–Aldrich syndrome, X-linked agammaglobulinemia, cyclic neutropenia, and IRAK-4/MyD-88 deficiency, were based on conventional, candidate–gene-driven immunological testing." (PMID 27703454, 2016).
epilepsy (2 papers, 2017 to 2025). A brain disorder characterized by episodes of abnormally increased neuronal discharge resulting in transient episodes of sensory or motor neurological dysfunction, or psychic dysfunction. "What is important is IRAK4, a genes associated with epilepsy, presented correlation with both miRs and whose dysregulation significantly related to poor survival in several human cancer." (PMID 28380454, 2017). "Furthermore, the mRNA levels of Irf3, Tlr4, Myd88, and Irak4 genes—encoding innate immune system markers essential for maintaining neuronal excitation/inhibition balance and implicated in epilepsy—were examined." (PMID 40608247, 2025). "Apart from the somatic mutations of IRAK4 itself, all indicated miRs may target single gene to interfere the process of cancer and epilepsy." (PMID 28380454, 2017).
glomerulonephritis (2 papers, 2019). A renal disorder characterized by damage in the glomeruli. "The IRAK4 inhibitor also reduced the concentration of anti-dsDNA and attenuated glomerulonephritis." (PMID 31694920, 2019).
gram-negative bacterial infections (2 papers, 2010 to 2025). Infections caused by bacteria that show up as pink (negative) when treated by the gram-staining method. "Complementing this, miR-203 also participates to immune regulation in fish via targeting IRAK4, which leads to the attenuation of inflammatory responses against Gram-negative bacterial infections." (PMID 40469308, 2025).
hepatocellular carcinoma (2 papers, 2022 to 2023). A malignant tumor that arises from hepatocytes. "Furthermore, there is evidence suggesting a correlation between genetic variations in IRAK4 and the occurrence of certain types of cancer, such as breast cancer, as well as the advancement of hepatocellular carcinoma (HCC) related to hepatitis B virus (HBV)." (PMID 38138875, 2023).
Hypoglycemia (2 papers, 2022 to 2023). A decreased concentration of glucose in the blood. "Two studies claimed that Irak4 (Interleukin-1 receptor associated kinase-4) controls hypoglycemia-induced glucagon secretion by modulating hypothalamic Il-1β signaling, and Agpat5 activation in AgRP (agouti-related protein) neurons leads to hypoglycemia-induced glucagon secretion." (PMID 37764697, 2023). "We confirmed that Irak4, by modulating hypothalamic Il-1β signaling, indeed controls hypoglycemia-induced glucagon secretion." (PMID 36180454, 2022). "We found that increased Irak4 expression, leading to increased Il-1ß signaling, reduced hypoglycemia-induced glucagon secretion." (PMID 36180454, 2022).
influenza infection (2 papers, 2021 to 2023). "IRAK4 kinase-dead knock-in (IRAK4KDKI) mice, which have a catalytically inactive form of IRAK4 that precludes MyD88-dependent signaling, were shown to be susceptible to influenza with a slight delay in the meantime to death compared to wildtype mice." (PMID 34282358, 2021). "The role of IRAK4, the first enzyme recruited to MyD88 for signaling, was also examined during influenza infection." (PMID 34282358, 2021).
influenza pneumonia (2 papers, 2014 to 2023). "The potential clinical relevance of S. pneumoniae lipoprotein-dependent inflammation was assessed in a mouse model of pneumonia, and using PBMCs from individuals with IRAK-4 deficiency." (PMID 25172490, 2014).
Liver fibrosis (2 papers, 2016 to 2025). "Liver fibrosis along with inflammatory changes observed in ABIN1[D485N] mice were drastically reduced after crossing to IRAK4[D329A] or IRAK1[D359A] mice but were not reduced by crossing to IFNAR1-KO mice." (PMID 27807192, 2016).
lupus nephritis (2 papers, 2016 to 2018). Glomerulonephritis in the context of systemic lupus erythematosus. "Our results support the notion that IRAK1 and/or IRAK4 are attractive targets for the development of drugs to prevent, and perhaps treat, lupus nephritis and other autoinflammatory diseases caused by the decreased ability of ABIN1 or other proteins to restrict the strength of MyD88 signaling." (PMID 27807192, 2016). "There are four SLEmetaSig100 genes (NFAIP3, IRAK4, MYD88, TLR4) in NF-kappa B signaling pathway that have been implicated in the pathogenesis of lupus nephritis coupled with upregulation of inflammatory cytokines." (PMID 29975701, 2018).
meningitis (2 papers, 2013 to 2016). A disorder characterized by acute inflammation of the meninges of the brain and/or spinal cord. "In contrast the observed increased IL-6 trend with the IRAK4 associated rs4251552 displays the opposite picture with a stronger pro-inflammatory response, which has been shown to be harmful for meningitis outcome." (PMID 27432718, 2016). "For meningitis outcome the rs2067085 in NOD2 (p = 5.1e − 04) and rs4251552 of IRAK4 were the strongest associations with unfavorable outcome (p = 6.7e − 04)." (PMID 27432718, 2016). "IRAK4- or MYD88-deficient patients are predisposed to recurrent invasive infections with S. pneumoniae, especially meningitis." (PMID 22996269, 2013).
myocarditis (2 papers, 2020 to 2023). Myocarditis is a condition that is characterized by inflammation of the heart muscle (myocardium). "In mice with myocarditis, IRAK4 deficiency improves heart functions and partially reverses the decrease in fractional shortening caused by CVB3 infection." (PMID 37175422, 2023). "Altogether, IRAK4 exacerbates myocarditis by decreasing the early influx of protective monocytes and macrophages to the heart, as well as inhibiting type 1 IFN production, which ultimately benefits viral replication." (PMID 37175422, 2023). "Furthermore, downstream activation of toll-like receptor signal regulators such as IRAK4 (interleukin-1 receptor associated kinase 4) leading to TRAF6 (tumor necrosis factor receptor-associated factor 6)-nuclear factor-κB activation can alter monocyte migration and accelerate myocarditis, too." (PMID 33329516, 2020). "Since IRAK4 negatively regulates Stat5, the major transcription factor of CCR5, it limits CCR5-dependent migration of monocytes to the heart during myocarditis." (PMID 37175422, 2023).
neutropenia (2 papers, 2012 to 2023). A decrease in the number of neutrophils found in the blood. "Seven of the hospitalized MyD88- or IRAK-4–deficient patients developed neutropenia during the acute phase of infection (three of four moderate cases and four of six critical cases), whereas only two had a high ANC at a particular time point (ANC > 8,000/mm3)." (PMID 36880831, 2023). "Interestingly, during acute or invasive infections, patients with MyD88 or IRAK-4 deficiency develop neutropenia despite having pus in infected tissues." (PMID 23209417, 2012). "Surprisingly, we observed frequent neutropenia (ANC < 1,500/mm3) in MyD88- or IRAK-4–deficient patients." (PMID 36880831, 2023). "Overall, IRAK-4– and MyD88-deficient patients were able to mount an inflammatory response to SARS-CoV-2 infection, with characteristic neutropenia potentially due to defective IL-1R signaling." (PMID 36880831, 2023).
synovitis (2 papers, 2021). Inflammation of a synovial membrane. "The purpose of this study is to look into the effects of adenovirus-mediated knockdown of IRAK4 on synovitis in the OA rabbit model." (PMID 34863246, 2021). "In sum, this study indicated that WB had obvious inhibitory effects on synovitis of CIA rats, and the mechanisms of which may be involved in downregulating the expression levels of several key proteins including MMP3, MMP19, LBP, IRAK4, and ARPC5." (PMID 34708132, 2021). "The role of IRAK4 in synovitis and its connection with the pathogenesis of OA is not clear." (PMID 34863246, 2021).
viral myocarditis (2 papers, 2023 to 2024). Myocarditis that is caused by an infection with a viral agent. "In fact, an adaptor known as interleukin-1-receptor-associated kinase-4 (IRAK-4) and acting downstream of proinflammatory MyD88 inhibits migration of inflammatory monocytes in experimental viral myocarditis." (PMID 39595580, 2024).
acute lung injury (1 paper, 2025). A condition of lung damage that is characterized by bilateral pulmonary infiltrates (pulmonary edema) rich in neutrophils, and in the absence of clinical heart failure. "Considering the critical function of IRAK4, the phosphorylation of IRAK4 was evaluated in an LPS-induced acute lung injury (ALI) model." (PMID 40771916, 2025).
AIDS (1 paper, 2022). A syndrome resulting from the acquired deficiency of cellular immunity caused by the human immunodeficiency virus (HIV). "We found that all of 3 IRAK isoforms (IRAK1, IRAK2, and IRAK4) we tested were highly expressed in AIDS-KS tissues when compared to those in normal skin tissues." (PMID 36457850, 2022).
Alzheimer disease (1 paper, 2020). A progressive, neurodegenerative disease characterized by loss of function and death of nerve cells in several areas of the brain leading to loss of cognitive function such as memory and language. "Examples include: PROTACs targeting interleukin-1 receptor-associated kinase 4 (IRAK4) for the treatment of autoimmune and inflammatory disease; PROTAC degraders of viral proteins for inhibition of the hepatitis C virus; and Tau degraders for the treatment of Alzheimer’s disease." (PMID 36046485, 2020).
apical periodontitis (1 paper, 2024). "Our findings contribute to a better understanding of the bone resorption process and suggest that inhibiting IRAK-4 could be a therapeutic strategy to combat oral infections caused by E. faecalis in apical periodontitis or other oral diseases characterized by bone destruction." (PMID 39126003, 2024). "The findings revealed significant differences in the percentages of the evaluated cells, highlighting the novel role of the IRAK-4 inhibitor in addressing this oral pathology, apical periodontitis, where bone destruction is observed." (PMID 39126003, 2024). "This approach could provide further insights into the specific interactions and responses within the local tissue microenvironment, contributing to a more nuanced understanding of the role of IRAK-4 in the context of apical periodontitis." (PMID 39126003, 2024). "Moreover, our investigation indicates that Thp-1 and macrophages from PBMCs of patients with apical periodontitis respond differently to the IRAK-4 inhibitor." (PMID 39126003, 2024). "Therefore, it might be in future studies to delve into the use of IRAK-4 inhibitors on macrophages isolates from gingival tissue and/or damaged tissue resulting from apical periodontitis." (PMID 39126003, 2024).
Arthritis (1 paper, 2018). Inflammation of a joint. "Small molecule inhibitors of interleukin-1 receptor-associated kinase 4 (IRAK4) were recently developed that block collagen-induced arthritis in mice." (PMID 30671484, 2018).
autoimmune encephalitis (1 paper, 2023). Inflammation of the brain secondary to an immune response triggered by the body itself. "A number of studies have described neuroinflammation in patients with IRAK-4 deficiency in the context of presumed infective/autoimmune encephalitis." (PMID 37744344, 2023).
cardiac arrest (1 paper, 2016). Cessation of breathing and/or cardiac function. "We observed significant positive correlation between both TLR2 and IRAK4 mRNA transcript levels and dosage of norepinephrine to maintain a mean arterial blood pressure ≥80 mmHg in the early phase after cardiac arrest." (PMID 27260481, 2016). "Serum lactate levels at the time of blood sampling were significantly positively correlated with TLR2 (rs 0.570; p = 0.001), TLR4 (rs 0.369; p = 0.045), IRAK3 (rs 0.569; p = 0.001), and IRAK4 (rs 0.413; p = 0.029) monocyte mRNA levels in the early phase after cardiac arrest." (PMID 27260481, 2016). "Nonsurvivors at 30 days had significantly lower mRNA levels of TLR2, IRAK3, IRAK4, NLRP3 and CASP1 in the late phase following cardiac arrest." (PMID 27260481, 2016). "Monocyte TLR2, TLR4, IRAK3, IRAK4, NLRP3, PYCARD and IL1B were initially upregulated in patients following cardiac arrest." (PMID 27260481, 2016). "Likewise, IRAK4, the main kinase to further promote TLR signaling activation, was upregulated in patients in the early phase after cardiac arrest." (PMID 27260481, 2016).
chronic myelogenous leukemia (1 paper, 2023). "In chronic myelogenous leukemia (CML), blocking NF-κB signals with IRAK-4 inhibition and BCR-ABL inhibition has been found to eliminate mouse and human CML leukemic stem/progenitor cells." (PMID 37954584, 2023).
cognitive decline (1 paper, 2021). "From our data, the expression IRAK-4, in response to inflammation, suggests its association with cognitive decline." (PMID 34199148, 2021).
depression (1 paper, 2024). "This, in part, may be due to the negative regulation of miR-93 on the interleukin receptor associated kinase-4 (IRAK-4), and in turn, suppression of inflammatory cytokines, posing a possible target for inflammation-associated depression." (PMID 38678012, 2024).
endometriosis (1 paper, 2019). The growth of functional endometrial tissue in anatomic sites outside the uterine body. "Furthermore, we demonstrated that neutralizing antibodies to IL-33 and/or IL-1R1, or an inhibitor of IRAK4 (involved in MyD88 signaling) were effective for the treatment of endometriosis in this model." (PMID 31507610, 2019). "Because the signal transduction pathway mediated by MyD88 was essential for endometriosis lesion formation, we investigated whether inhibition of IRAK4 (an essential protein kinase for this pathway) provided an effective treatment." (PMID 31507610, 2019). "Finally, we found that an IRAK4 inhibitor suppressed the onset and growth of endometriosis." (PMID 31507610, 2019).
Familial hemophagocytic lymphohistiocytosis (1 paper, 2025). Familial Hemophagocytic lymphohistiocytosis (FHL) is a rare primary immunodeficiency characterized by a macrophage activation syndrome (see this term) with an onset usually occurring within a few months or less common several years after birth. "The steep early decline in survival we observed in patients with disorders of immune regulation and innate IEI may argue for an extension of NBS to other immediately life-threatening IEI (e.g., familial hemophagocytic lymphohistiocytosis [FHL], XLP1, MyD88/IRAK4 deficiencies, and IPEX syndromes)." (PMID 41347188, 2025).
Fever (1 paper, 2017). Body temperature elevated above the normal range. "Exogenous pathogens activate the TLRs signaling pathway constituents such as TLR4, MyD88, TBK1, IRF3, and IRAK4, and subsequently stimulate the release of pro-inflammatory cytokines which promote to progress a disease by producing fever and tissue damage." (PMID 28489052, 2017).
gastritis (1 paper, 2024). Inflammation of the stomach. "Caffeic acid exerts anti-gastritis effects by inhibiting interleukin-1 receptor-associated kinase 1 (IRAK1), interleukin-1 receptor-associated kinase 4 (IRAK4), and TAK1 by interfering with the JNK/MAPK pathway." (PMID 38975345, 2024).
gingivitis (1 paper, 2019). A disorder involving inflammation of the gums; may affect surrounding and supporting structures of the teeth. "MyD88, IRAK2, IRAK4 (MyD88-dependent), and TBK1 (MyD88-independent) were significantly up-regulated in RHG exposed to commensal biofilm compared to gingivitis or cariogenic biofilms." (PMID 31448244, 2019). "In comparison, gingivitis biofilm activated fewer genes (e.g., TLR4) and cariogenic biofilm suppressed CD14, IRAK4, and IRF3 transcription." (PMID 31448244, 2019). "Besides the upregulation induced by the commensal biofilm, we also found that gingivitis biofilm significantly up-regulated CD14; gingivitis and cariogenic biofilms both up-regulated IRAK2 transcription; while the cariogenic biofilm slightly suppressed CD14, IRAK4, and IRF3 transcription." (PMID 31448244, 2019).